UCP2 (uncoupling protein 2)
Diseases named in the same sentence as UCP2 in open-access papers (continued):
Sharing a sentence is not in itself a finding about the gene and the disease.
cholangiocarcinoma (4 papers, 2020 to 2024). A carcinoma that arises from the intrahepatic biliary tree (intrahepatic cholangiocarcinoma) or from the junction, or adjacent to the junction, of the right and left hepatic ducts (hilar cholangiocarcinoma). "In human cholangiocarcinoma, up-regulation of uncoupling protein 2 (UCP2) associated with increased glycolysis, lymph node invasion, and poor prognosis have been observed." (PMID 32252351, 2020). "Moreover, activated AMPK reversed the mesenchymal phenotype by inhibiting Akt signaling in cholangiocarcinoma cell lines with low UCP2 expression." (PMID 36499405, 2022). "However, in post-resection in situ livers, both UCP2 and 4-HNE immunoscore levels were significantly elevated in cholangiocarcinoma patients compared to all other indications combined (190.0 vs. 151.9; p = 0.021 and 163.3 vs. 119.9; p = 0.005)." (PMID 38790695, 2024).
glioblastoma (4 papers, 2015 to 2025). The most malignant astrocytic tumor (WHO grade IV). "Small-molecule inhibitors of UCP2, such as genipin, have demonstrated preclinical efficacy in other cancer types, supporting further evaluation in glioblastoma models." (PMID 41403699, 2025). "Experimental validation in glioblastoma models confirmed that UCP2 knockdown attenuated EMT, impaired invasion, and improved radiosensitivity." (PMID 41403699, 2025). "Our findings, primarily derived from bioinformatics and in vitro studies, underscore UCP2 as a candidate therapeutic target and highlight novel avenues for future research to improve glioblastoma treatment." (PMID 41403699, 2025). "In vitro experiments were carried out to assess UCP2’s impact on glioblastoma (GBM) aggressive traits and apoptosis." (PMID 41403699, 2025). "The elevated expression of UCP2 in multiple malignancies, including glioblastoma, suggests its potential involvement in tumorigenesis and progression." (PMID 41403699, 2025). "In summary, our work provides a foundational framework for future research on UCP2-targeted strategies, highlighting its promise as a therapeutic target for glioblastoma (GBM)." (PMID 41403699, 2025). "Functional experiments demonstrated that UCP2 knockdown inhibits EMT, migration, and invasion in glioblastoma cells, while increasing apoptosis induced by irradiation." (PMID 41403699, 2025). "Consistent with previous findings, UCP2 expression was shown to be significantly greater in GBM tissue than non-tumor tissue in an analysis of the TCGA GBM database containing 10 non-tumor samples and 528 Glioblastoma samples (p<0.05)." (PMID 33763373, 2021).
Hypoglycemia (4 papers, 2011 to 2023). A decreased concentration of glucose in the blood. "UCP2 (mitochondrial uncoupling protein 2) mutations were recently reported in two unrelated children with neonatal-onset congenital HI and hypoglycemia which were diazoxide-responsive." (PMID 21967988, 2011). "Circadian-like UCP2 activity linked to glucose-induced ATP production has been observed in mouse pancreatic islets and β cells, with the upregulation of UCP2 in the resting (light) phase preventing hypoglycemia." (PMID 36978924, 2023). "A previous study found that inhibition of UCP-2 by genipin reduced hypoglycemia-induced glucagon secretion from pancreatic α-cells, thereby slowing the rate of blood glucose recovery during an insulin tolerance test." (PMID 36768454, 2023). "Further studies are needed to assess the role of UCP2 or other pathways in mitochondrial remodeling with hypoglycemia in GHRH and other GI neurons." (PMID 33148883, 2020).
kidney damage (4 papers, 2017 to 2023). "The assessment of proteinuria showed that brain overexpression of UCP2 caused a substantial protection of early kidney damage in JD-fed SHRSP rats." (PMID 32560241, 2020). "We were surprised to find that selective UCP2 overexpression in the striatum was highly protective against early kidney damage in JD-fed SHRSP rats." (PMID 32560241, 2020). "Remarkably, brain overexpression of UCP2 did not change BP in SHRSP rats, raising the intriguing possibility that UCP2 expression in striatal neurons and perhaps other CNS neurons drives a protective mechanism against kidney damage, which does not involve the regulation of BP." (PMID 32560241, 2020).
lipid metabolism disorders (4 papers, 2013 to 2025). "CIH mainly affected the transcription levels of the PPARγ, ACOX1, and UCP2 genes and further aggravated the HFD‐induced lipid metabolism disorders." (PMID 39229924, 2024).
Myocardial fibrosis (4 papers, 2021 to 2025). "Expanding on the protective mechanisms, Han Wu’s experiments on STZ-induced diabetic mice revealed that RES prevents myocardial fibrosis by regulating the bone morphogenetic protein signaling pathway, inhibiting UCP2 expression, and reducing ROS production." (PMID 39551777, 2024). "To explore the potential mechanism of UCP2 in alleviating myocardial fibrosis, we detected the expression of fibrosis-related proteins (MMP9 and TGF-β) by WB." (PMID 35284500, 2021).
pancreatitis (4 papers, 2014 to 2025). Inflammation of the pancreas. "The high expression of UCP2 suggested increased pancreatic follicular cell damage and a higher degree of pancreatitis." (PMID 39707176, 2024). "Together, both approaches argue against the possibility that functional defects of pancreatic acinar cells are responsible for the increased severity of cerulein pancreatitis in 12 months old UCP2-/- mice." (PMID 24721982, 2014). "Together, these data point to effective mechanisms of antioxidative defense in pancreatic acinar cells and suggest that the increased severity of cerulein pancreatitis in UCP2-/- mice is unrelated to the investigated acinar cell functions." (PMID 24721982, 2014). "In conclusion, UCP2 may be an important therapeutic target for pancreatitis and a key focus for future research." (PMID 39707176, 2024). "Some studies also showed that UCP2 overexpression may be deleterious in acute liver injury and pancreatitis." (PMID 27057102, 2016).
rheumatoid arthritis (4 papers, 2022 to 2025). A chronic, systemic autoimmune disorder characterized by inflammation in the synovial membranes and articular surfaces. "One study employed macrophage corpses as drug delivery vehicles to activate AMPK and indirectly upregulate UCP2 for the treatment of rheumatoid arthritis, a strategy that may also be applicable to KOA." (PMID 40083558, 2025). "The UCP2 (uncoupling protein 2) –866 G/A polymorphism, a gene involved in both mitochondrial ATP production and reactive oxygen species (ROS) generation, has been associated with SLE and rheumatoid arthritis." (PMID 37554724, 2023).
acute myeloid leukemia (3 papers, 2022 to 2025). Acute myeloid leukemia (AML) is a group of neoplasms arising from precursor cells committed to the myeloid cell-line differentiation. "Mechanistically, in vitro and in vivo silencing of UCP2 significantly impairs acute myeloid leukemia cell growth and survival, accompanied by the disruption of mitochondrial homeostasis." (PMID 42004221, 2025). "More importantly, supplementation of BCAA enhanced the anti-tumor activity of genipin, a selective inhibitor that targets UCP2, resulting in significantly reduced acute myeloid leukemia blasts, increased mouse survival, and magnified oxidative stress." (PMID 42004221, 2025). "Herein, we demonstrated that UCP2 was highly expressed in AML and significantly associated with poor prognosis and chemoresistance, suggesting that UCP2 can be used as a potential biomarker in acute myeloid leukemia." (PMID 42004221, 2025).
acute pancreatitis (3 papers, 2019 to 2024). An acute inflammatory process that leads to necrosis of the pancreatic parenchyma. "Despite this, UCP2’s role in acute pancreatitis (AP) remains underexplored, and its functions in chronic pancreatitis (CP) and pancreatic steatosis are largely unknown." (PMID 39707176, 2024). "Studies have confirmed that irisin may alleviate mitochondrial damage and reduce the production of ROS to inhibit oxidative stress by regulating the expression of UCP2, thereby reducing lung ischemia-reperfusion injury and severe acute pancreatitis injury." (PMID 34697562, 2021).
Anxiety (3 papers, 2022 to 2025). Intense feelings of nervousness, tension, or panic often arise in response to interpersonal stresses. "A recent study indicated that UCP2 loss in microglia results in anxiety phenotypes in male mice, therefore we annotated sex as an additional factor in the PC space." (PMID 37731609, 2023). "Ucp2 knock-out animals consistently demonstrate bLR-like behaviors, including decreased exploration, and anxiety- and depressive-like behaviors, especially following stress." (PMID 40103584, 2025). "UCP2, moreover, plays an essential role in the development of cognitive ability and resistance to anxiety." (PMID 36733695, 2022). "The blockade of UCP2, on the other hand, produces cognitive impairment and anxiety in young mice." (PMID 36733695, 2022).
bladder carcinoma (3 papers, 2013 to 2020). "Likewise, UCP2 inhibition by genipin or UCP2 mRNA silencing strongly enhances gemcitabine-induced mitochondrial superoxide generation and apoptotic cell death of pancreatic, lung and bladder cancer cell lines." (PMID 23966948, 2013).
breast invasive cancer (3 papers, 2020 to 2022). "We found ER stress markers upregulated in breast invasive cancer tissues with high expression of UCP2 and prostate adenocarcinoma with low expression of UCP2." (PMID 33614647, 2021). "We found similar results as for breast invasive cancer, including an upregulation of UCP2 and a significant downregulation of four out of six genes associated with mitochondrial-ER interaction stabilization." (PMID 33614647, 2021). "These in vitro findings were further supported by the inverse expression pattern between proteins stabilizing mitochondrial-ER linkage and UCP2 in human invasive breast cancer and pancreatic adenocarcinoma tissues." (PMID 33614647, 2021). "Besides, TCGA analysis revealed an inverse expression correlation between proteins stabilizing mitochondrial-ER linkage and UCP2 in tissues of human breast invasive cancer and prostate adenocarcinoma." (PMID 33614647, 2021). "Genes specifically differentially methylated in invasive breast cancer, UCP2 and SSBP1, show no change in gene expression in DCIS but significant change in gene expression in invasive breast cancer tissue from human clinical samples." (PMID 32051475, 2020).
breast tumor (3 papers, 2011 to 2023). "TGF-β has been reported to reduce mitochondrial complex IV in lung epithelial cells and regulate mitochondrial UCP2 in breast tumor cells expression." (PMID 37270534, 2023). "The study presented in this paper suggests that UCP2 expression was up to 800-fold higher in primary breast tumors when compared with paired normal breast tissues." (PMID 21935467, 2011). "In breast tumor cell lines, loss of TGF-β/SMAD dependent signaling could promote UCP2 expression; facilitate reduction of mitochondrial ROS production and thus augmenting tumor cell survival and proliferation." (PMID 23185428, 2012).
colon adenocarcinoma (3 papers, 2012 to 2022). "Ras oncoproteins also directly increase the expression of uncoupling protein (UCP)-1, and UCP-2 expression has been found to be increased in most human colon adenocarcinomas in which up to 60% contain K-Ras mutations." (PMID 22917272, 2012). "Although UCP2 was rarely detected in hyperplastic polyps (11%), it was present in tubular adenomas (58.8%) and colon adenocarcinomas (86.0%)." (PMID 22292025, 2012).
experimental autoimmune encephalomyelitis (3 papers, 2008 to 2012). An autoimmune demyelinating disease of the central nervous system that is produced experimentally in animals by the injection of homogenized brain or spinal cord in Freund's adjuvant. "UCP2 has been reported to play a role in MS and its animal model, Experimental Autoimmune Encephalomyelitis (EAE), and its role in affecting reactive oxygen species (ROS) production in mitochondria has been proposed to be a potential mechanism." (PMID 18270557, 2008). "An increase of UCP2 mRNA levels in the course of mice experimental autoimmune encephalomyelitis was reported, however, it could not be determined whether UCP2 is increased due to spinal cord infiltration by immune cells or as a result of neuronal expression of UCP2." (PMID 22870219, 2012).
hyperuricemia (3 papers, 2016 to 2022). An abnormally high level of uric acid. "UCP2 has been reported to be associated with serum urate concentrations, as well as with hyperuricemia." (PMID 35372350, 2022). "It has been previously suggested that the interaction between CPT2 and UCP2 is associated with gout or hyperuricemia." (PMID 35372350, 2022). "This present study identified a novel gene, UCP2, that influences the serum urate concentration and the risk of hyperuricemia, and the degree of association varies with gender and BMI levels." (PMID 27273589, 2016). "This study aimed to investigate the association between UCP2 variants and serum urate as well as hyperuricemia in a Chinese population." (PMID 27273589, 2016). "In the present study, we first focused on the relationship between UCP2 variants and serum urate and hyperuricemia, potentially examining the scope of the loci related to hyperuricemia." (PMID 27273589, 2016). "In the present study, we found UCP2 variants −866G/A and Ala55Val had a stronger effect on females with hyperuricemia." (PMID 27273589, 2016). "Further analysis was performed regarding the genetic effect of UCP2 variants on serum urate and the risk of hyperuricemia among females with different BMI levels." (PMID 27273589, 2016). "The present study identified a novel gene, UCP2, with two loci, −866G/A and Ala55Val; this gene influenced the serum urate concentrations and the risk of hyperuricemia in females." (PMID 27273589, 2016). "Similar to −866G/A, the protective role of the Ala55Val variant for hyperuricemia might also be attributed to altered UCP2 transcription." (PMID 27273589, 2016). "Females with the A allele, which is associated with higher UCP2 mRNA expression, had lower serum urate and a decreased risk of hyperuricemia, but no relation was found in males." (PMID 31064394, 2019).
ischemic stroke (3 papers, 2020 to 2021). A stroke disorder caused by obstruction of blood flow to the brain, due to thrombotic (local blood clot formation) or embolic (due to a blood clot or other material traveling from another site) event. "Another potential target involved in regulating mitochondrial MPTP in ischemic stroke was mitochondrial uncoupling protein 2 (UCP-2)." (PMID 32269527, 2020). "Decreased mitochondrial uncoupling protein-2 (UCP2) activity and enhanced BDNF expression are other pathways mediated through SIRT1 regulation that protect neurons in ischemic stroke." (PMID 32727328, 2021).
lactic acidosis (3 papers, 2014 to 2022). Metabolic acidosis characterized by the accumulation of lactate in the body. "Depletion of UCP2 in mtDNA mutator mice led to further shortening of the lifespan with earlier signs of mitochondrial cardiomyopathy accompanied with high systemic lactic acidosis, often used as a marker of mitochondrial diseases." (PMID 24945157, 2014). "Instead, we show that UCP2 promotes fatty acid oxidation in heart, while also protecting from lactic acidosis resulting from systemic respiratory deficiency." (PMID 24945157, 2014). "Lactic acidosis, as detected in DM mice, is a common symptom in patients with mitochondrial diseases and is largely postponed in mtDNA mutator mice as a consequence of UCP2 overexpression." (PMID 24945157, 2014). "As cultured cells prefer glucose substrate utilization, an increase in oxidative phosphorylation of glucose by UCP-2 would be beneficial, by providing the cells with enough energy and limiting lactic acidosis." (PMID 32120777, 2020). "Instead, our results argue that high UCP2 levels allow better utilization of fatty acid oxidation resulting in a beneficial effect on mitochondrial function in heart, postponing systemic lactic acidosis and resulting in longer lifespan in these mice." (PMID 24945157, 2014).
lung adenocarcinoma (3 papers, 2016 to 2023). A carcinoma that arises from the lung and is characterized by the presence of malignant glandular epithelial cells. "We have examined the role of UCP2 in the energy metabolism of the lung adenocarcinoma cell line A549 and show that UCP2 silencing decreased the basal rate of respiration, although this inhibition was not compensated by an increase in glycolysis." (PMID 37175829, 2023). "Here, we investigate the effect of UCP2 silencing on the energy metabolism of the human lung adenocarcinoma cell line A549." (PMID 37175829, 2023). "UCP2 mRNA expression was higher in lung adenocarcinomas (RQ = 0.053, 0.03–0.087, N = 61) than in SqCLCs (RQ = 0.035, 0.019–0.072, N = 75, Mann–Whitney test, p = 0.015)." (PMID 28258342, 2017). "UCP2 was found to regulate the energy metabolism in stem cells and the induction of UCP2 expression was shown to reduce the mitochondrial membrane potential and ROS production in A549 lung adenocarcinoma cells in which it also induced a shift in the cellular metabolism." (PMID 27128320, 2016).
prediabetes (3 papers, 2018 to 2025). "Little is known with regard to the association between UCP2/UCP3 polymorphisms and T2DM or prediabetes in Chinese population." (PMID 29529994, 2018). "In this study, three SNPs of UCP2 and six SNPs of UCP3 were genotyped and the associations between these SNPs and T2DM or prediabetes were evaluated in a rural Chinese population." (PMID 29529994, 2018). "The haplotypes, gene-environmental interaction and association between genetic variants of UCP2 and UCP3 and prediabetes or T2DM were explored." (PMID 29529994, 2018). "In the current study, we used bioinformatics analyses to identify and select a set of variants in the UCP2/UCP3 region to determine the association between UCP2/UCP3 and prediabetes or T2DM in a Chinese population." (PMID 29529994, 2018). "The study was to examine the associations of genetic variants of UCP2 and UCP3 with prediabetes and T2DM in a rural Chinese population." (PMID 29529994, 2018).
promyelocytic leukemia (3 papers, 2018 to 2025). "Chemical induction of S-glutathionylation of uncoupling protein-2 (UCP2), which is over-expressed in several cancer types to confer resistance to oxidative distress, sensitizes drug-resistant promyelocytic leukemia cells to chemotherapeutic agents." (PMID 40358176, 2025). "S-glutathionylation of UCP2, which is more ubiquitously expressed, was found to regulate insulin release by altering mitochondrial ROS release in pancreatic β-cells and sensitize drug resistant promyelocytic leukemia cells to chemotherapy." (PMID 29444156, 2018).
retinal disease (3 papers, 2015 to 2022). "The overexpression and knockout studies of UCP2 in mice have established the ability of this protein to provide neuroprotection in a number of animal models of neurological disease, including retinal diseases." (PMID 35628482, 2022). "It is also among the first to review the evidence that small molecule activators of UCP2 can prevent neuronal death in an animal model of retinal disease." (PMID 35628482, 2022). "Our results open new perspectives for understanding the UCP2-modulating mechanisms of mitochondrial activity in normal retina, as well as in retinal disease." (PMID 25951172, 2015). "Regardless, a larger study of Ucp2 and PPAR-γ in retinal disease that uses multiple models and agonists/antagonists may yield a clearer picture that captures the cell type specific dynamics of these factors, and changes during different paradigms of retinal damage." (PMID 30906248, 2019).